FASN (fatty acid synthase)
Diseases named in the same sentence as FASN in open-access papers (continued):
Sharing a sentence is not in itself a finding about the gene and the disease.
cancer (continued). "When the expression level of fatty acid synthase is low, CCA cells provide FAs for cancer development and progression by increasing the expression of FA uptake-related proteins." (PMID 39984452, 2025). "In breast and prostate cancers, an inhibitor of fatty acid synthase reduces epithelial simvastatin statin, which inhibits cholesterol synthesis, reduces EMT markers, and improves radiosensitivity in several cancers." (PMID 40895189, 2025). "Deacetylation stabilizes FASN, allowing it to bind more effectively with TRIM21, thereby reducing lipogenesis and inhibiting cancer cell growth." (PMID 39944823, 2025). "The production of fatty acids, primarily orchestrated by fatty acid synthase (FASN), is frequently upregulated and excessively active in malignant tumors, contributing to their growth and spread." (PMID 41278297, 2025). "Key enzymes and transporters involved in lipid metabolism, such as CPT1, FASN, and fatty acid transport proteins, are influenced by exercise, resulting in a shift from glucose metabolism to lipid oxidation, which may reduce the metabolic flexibility of cancer cells." (PMID 40487761, 2025). "SREBP1 directly binds to the promoters of ACC1 and FASN, highlighting the important role of SREBP1‐mediated de novo lipogenesis in cancer progression." (PMID 39425259, 2025). "For lipid metabolism, key enzymes such as ACC, FASN, SCD, and ACS are affected by lncRNAs, resulting in lipid uptake, storage, and catabolic reprogramming, through which cancer cells obtain important raw materials for tumor growth and progression." (PMID 38184562, 2024). "The expression of various lipid synthases is elevated in cancer cells, including sterol regulatory element binding proteins (SREBPs), ATP-citrate lyase (ACLY), acetyl-CoA carboxylase (ACC), fatty acid synthase (FASN), and stearoyl-CoA desaturase 1 (SCD1)." (PMID 38994204, 2024). "Lipogenic enzymes, including ATP citrate lyase, acetyl-CoA carboxylase, and fatty acid synthase (FASN), have elevated expression and activity in cancer cells, which exacerbates lipogenesis." (PMID 38566208, 2024). "Lipid metabolic pathways, including fatty acid synthase (FASN) and stearoyl-COA desaturase (SCD) signaling, also sustain cancer stem cells in HCC, contributing to metastasis and drug resistance." (PMID 38297372, 2024). "This is also reflected by the correlation (ELOVL5, FADS2 and ACSL4) and anti-correlation (FASN and SCD) of these enzymes with Zeb1 expression in cancer cell lines." (PMID 39009641, 2024). "At the molecular level, key lipogenic enzymes, such as acetyl-CoA carboxylase (ACC) and fatty acid synthase (FASN), are upregulated in HCC and other cancers, enhancing fatty acid synthesis and promoting tumor cell survival." (PMID 38698462, 2024). "Overexpression of fatty acid synthase (FASN) occurs in multiple cancers, which indicates a potential role of dysregulated fatty acid synthesis in cancer metabolism." (PMID 39609706, 2024). "O-GlcNac production may be directly modulated by nutrient flux and intracellular metabolism; however, the impact of de novo lipogenesis via FASN upregulation on hexosamine metabolism-associated enzymes and O-linked protein glycosylation in cancer cells has not been reported." (PMID 38732103, 2024). "Validation in TCGA datasets revealed significant correlations between LRP1, FASN, SIRT6, and clinical outcomes in BC patients, suggesting their potential as cancer biomarkers." (PMID 39071712, 2024). "Cancer cells activate lipogenic enzymes, including ATP-citrate lyase (ACLY), acetyl-CoA carboxylase (ACC), CoA carboxylase (ACACA), fatty acid synthase (FASN), and SCD, resulting in increased production of fatty acids." (PMID 38765144, 2024). "Cancer cells exhibit increased de novo adipogenesis due to elevated expression of lipogenic enzymes like ATP citrate lyase (ACLY) and fatty acid synthase (FASN)." (PMID 38782774, 2024).
cancer (continued). "With the change of lipid metabolism, FASN and PGE2 in cancer cells can induce TAM to M2 phenotypic polarization, while 27-HC secreted by TAMs can promote cancer cell proliferation and promote monocytes to differentiate into M2 macrophages." (PMID 39192979, 2024). "Key regulators of adipogenesis, including sterol regulatory element binding protein (SREBP), acetyl coenzyme A carboxylase (ACC), FASN and stearoyl coenzyme A desaturase 1 (SCD-1), are detected to be significantly up-regulated in various human cancers." (PMID 38434684, 2024). "The dysregulated expression observed in various cancers positions SIRT6, LRP1, and FASN as potential candidates for cancer biomarkers." (PMID 39071712, 2024). "Several FASN inhibitors, including cerulenin, orlistat, C75, fasnall, and TVB-2640, have been tested against cancer in preclinical studies." (PMID 38953350, 2024). "Validation in TCGA datasets highlighted the prognostic significance of LRP1, FASN, and SIRT6, suggesting their potential as cancer biomarkers." (PMID 39071712, 2024). "In a variety of cancer types, a considerable number of drugs that can inhibit the synthesis of SREBP, ACLY, ACC, FASN, SCD, and PPARα have been tested for anticancer effects in preclinical and clinical studies." (PMID 38189049, 2023). "The key enzymes of lipid biosynthesis, FASN, ACC, and SCD1 play important roles in the tumorigenesis of various cancers." (PMID 37046804, 2023). "We analyzed FASN and SREBP1 gene expression across several cancer types by analyzing the Cancer Genome Atlas (TCGA) dataset." (PMID 37444561, 2023). "An exquisite mechanism is observed in cancer cells during hypoxia to promote the expression of lipogenic genes acetyl-CoA carboxylase alpha (ACACA) and fatty acid synthase (FASN), by mean of the acetate mediated histone H3 acetylation." (PMID 37404756, 2023). "Increased levels of FASN and ACLY contribute to cancer stem cell-like properties, self-renewal induction, cellular steatosis, affecting HCC progression." (PMID 38189049, 2023). "ACLY, FASN, SCD, and ACC are considered key enzymes for fatty acid synthesis and have been reported to promote proliferation in several types of cancers." (PMID 37821935, 2023). "SREBPs regulate fatty acid and cholesterol metabolism, and their targets genes, such as fatty acid synthase (FASN) and stearoyl-CoA desaturase-1 (SCD1), are therapeutic targets in many cancers." (PMID 37885013, 2023). "Together, these data corroborate and strengthen the differential expression of FASN in PDAC and PCa, a higher expression of FASN was observed in PCa than in PDAC and correlated with a worse prognosis in this cancer setting." (PMID 36650542, 2023). "In castration-resistant cancer cell lines, decreased tumor growth, increased apoptosis, altered lipidome, decreased lipid storage, and AR and AR-V7 expression have been observed after inhibiting FASN activity, thus highlighting the role that this enzyme may play in PCa progression." (PMID 36674430, 2023). "Cancer cells rely on regulating SREBP1 expression as well as activating both SCD1 and FASN to promote lipogenesis and proliferation." (PMID 38189049, 2023). "Specifically, targeting key enzymes involved in fatty acid synthesis (SREBP, ACLY, ACC, FASN, and SCD) has been identified as a potential strategy for cancer therapy." (PMID 38189049, 2023). "In another study, it was found that FASN overexpression enhanced the cellular respiration (e.g., FAO) that favors cancer cells during CRC." (PMID 37190124, 2023). "Nevertheless, the fatty acids synthase (FASN) is overexpressed in NSCLC and its inhibition leads to a diminution of lactate and ATP production, as well as cancer proliferation, invasion and migration." (PMID 37180110, 2023). "Our data reveal upstream regulation layers of FASN and illustrates how oncogenic signals from EGF-CSN6 link FBXW7β-FASN axis for promoting lipogenesis and tumorigenesis in cancer." (PMID 37202390, 2023).
cancer (continued). "This pathway is controlled by lipogenic metabolic enzymes, including ATP-citrate lyase (ACLY), acetyl-CoA carboxylase (ACC) and fatty acid synthase (FASN), which are upregulated in some cancer cells." (PMID 37444561, 2023). "In many cancer systems, de novo lipogenesis proteins ATP-citrate lyase (ACLY), acetyl-CoA carboxylase 1 (ACC1), and fatty acid synthase (FASN) have been reported to be upregulated." (PMID 38069382, 2023). "PGG suppressed the growth of MDA-MB-231 cells by downregulating fatty acid synthase (FAS); this enzyme activates caspase-3 and is highly expressed in some cancers." (PMID 37375411, 2023). "Several FASN-specific inhibitors such as cerulenin, C75, orlistat, and TVB-2640/3166/3664 have been developed for cancer targeted therapy." (PMID 37120513, 2023). "Expression of key lipogenic enzymes, including FASN, is often regulated by the mTOR-SREBP1 axis in cancer cells." (PMID 37444561, 2023). "Results showed that FASN expression was prognostic for the OS, DSS, and PFI of many types of cancers, especially for male cancer patients." (PMID 37696831, 2023). "FASN exhibited differential expression patterns in PDAC and PCa, suggesting a different evolution during cancer progression." (PMID 36650542, 2023). "Fatty acid synthase (FASN) is highly expressed in multiple types of human cancers and is recognized as one of the targets for treating cancer metastasis." (PMID 35566090, 2022). "Inhibition of key enzymes for FAs synthesis, such as FASN (presented above), ATP-citrate lyase (ACLY) and ACC can decrease the proliferation and growth of different cancer cells." (PMID 35433453, 2022). "Concisely, the mRNA and protein expression level of FASN and FADS2 was upregulated in ZEB1 overexpression cancer cells, while downregulated in the ZEB1-S555A mutant cells." (PMID 35844792, 2022). "Well‐known FASN inhibitors, including cerulenin, C75 and orlistat, suggest the DNL pathway as an attractive therapeutic target for cancer." (PMID 35243817, 2022). "Some independent studies have shown that FASN serves as an oncogenic factor and enhances LNM in multiple types of cancer." (PMID 35597782, 2022). "To detect the role of USP13-FASN axis in regulating cancer stemness and lipogenesis in SCLC, we stably depleted FASN after WT USP13 reconstitution in USP13 knockdown cells." (PMID 35898882, 2022). "Given its role in FASN mRNA and protein expression, we next explored the role of SRPK2 in de novo palmitate synthesis in cancer cells in response to IGF-1 exposure." (PMID 36096767, 2022). "The impact of PPARγ on cancers is complex and bidirectional, PPARγ acts as a tumor promoter by induction of lipogenic gene ACLY, MIG12, FASN, and NR1F1, stem cell-related gene KLF4, ALDH and upregulation Nox1 ROS, and VEGF." (PMID 36587194, 2022). "FASN-overexpressed cells often show decreased AMPK, and FASN inhibition has been shown to re-activate AMPK in different cancer types." (PMID 35742944, 2022). "FASN consumes acetyl-CoA, malonyl-CoA and NADPH to catalyze the biosynthesis of palmitate, sustaining altered metabolic state for cancer growth and survival." (PMID 35646898, 2022). "The key factors which are closely linked with tumor microenvironment (TME) metabolic alterations in RCC include HIF, fatty acid synthase (FASN) and pyruvate kinase 2 (PKM2), being potential targets in cancer therapy." (PMID 35912170, 2022). "Fatty Acid Synthase (FASN), a key enzyme of de novo lipid synthesis, has been actively investigated as a therapeutic target in cancer." (PMID 35742953, 2022). "Based on these molecular mechanism findings, we screened drugs targeting FASN and SREBF1 from the Cancer Therapeutics Response Portal (CTRP), Genomics of Drug Sensitivity in Cancer (GDSC), and CellMiner databases." (PMID 35392075, 2022). "Cancer cells form a capable nascent FAS mechanism with the increased activity of key adipogenic enzymes (e.g., acetyl-CoA carboxylase (ACC) and fatty acid synthase (FASN))." (PMID 35785165, 2022).
cancer (continued). "The findings also showed that the mRNA expression levels of TM4SF1, FASN, and IMPDH1 were higher in cancer tissues, whereas the mRNA expression of KCNJ15 was higher in normal tissues." (PMID 35480865, 2022). "Dysregulation of GLUT-1/3, HK II, PFK-1 CPT1/2, FASN and GLS1 is common in most cancer types, and the interlinked metabolic pathways compensate for the deprivation of nutrients to maintain cancer growth, proliferation, and metastasis." (PMID 36618350, 2022). "At present, only TVB-2640 is the first clinically tested selective and potent FASN inhibitor, and is being included in the clinical trial (ClinicalTrials.gov: NCT02223247) of paclitaxel combined cohorts in cancer treatment." (PMID 39086974, 2022). "Fatty acid synthase (FASN), the key regulatory enzyme of lipogenesis, and acetyl-CoA carboxylase (ACC), are upregulated in many cancer types." (PMID 36618350, 2022). "Targeting FA synthesis (FASN), oxidation (CPT1), or uptake (CD36) sensitizes cancer cells to chemotherapy in adult models." (PMID 35764645, 2022). "Similar KID interactions with fatty acid synthase (FASN) and PUMA all promote pro-survival in cancer cells." (PMID 36497413, 2022). "The enzymes of lipogenesis are increased in various cancers, including HCC, such as ATP citrate lyase (ACLY), acetyl-CoA carboxylase (ACC), fatty acid synthase (FASN), acyl-CoA synthease (ACS) and stearoyl-CoA-desaturase 1 (SCD1)." (PMID 36612019, 2022). "SREBP-1 is a key molecule in regulating the production of fatty acids and triglycerides through stimulating the expression of FASN and ACACA, which increases cancer cell viability and promotes tumor growth." (PMID 36496421, 2022). "Fatty acid synthase (FASN) is an enzyme involved in fatty acid synthesis and is a key player in the tumorigenesis of several cancers." (PMID 36011029, 2022). "The co-occurrence of DGAT1 amplification with FASN, CD36, or MAGL amplification in human cancers was significant, arguing for these co-aberrations being synergistic, in keeping with DGAT1 facilitating safe accumulation of FA in cancer cells." (PMID 35732120, 2022). "Simultaneously, we found that the expression of FASN was correlated with various chemokines (e.g., XCL2 and CCL14) and chemokine receptors (e.g., XCR1 and CCR8) in different cancers." (PMID 36555243, 2022). "Fatty acid synthase (FASN), the single cytosolic enzyme applies for de novo synthesis of long-chain saturated fatty acids and is essential for cancer cell survival." (PMID 36230935, 2022). "Considering that lipids are important components of cell membranes and signaling molecules during cancer cell proliferation and progression, it is necessary to target lipogenic enzymes, including SCD1, FASN and ACC, for cancer treatment." (PMID 35642041, 2022). "That is the case with FASN, whose activity is positively correlated with the positivity of the HER2 marker, cancer progression and chemoresistance." (PMID 36551752, 2022). "A result of increased FAs synthesis by activation of FASN, or increased FAs uptake by upregulating SRA, will lead to an inhibition in the ability of DCs to support antitumor T cells in cancer." (PMID 34766135, 2021). "The rate-limiting enzymes in fatty acid synthesis, such as fatty acid synthase (FASN) and acetyl-CoA carboxylase (ACC), have been reported to be overexpressed and involved in the promotion of cancer progression." (PMID 34839347, 2021). "The most important enzymes in lipid metabolism, such as Acetyl-CoA Carboxylase (ACC), Fatty Acid Synthase (FASN), ATP Citrate Lyase (ACLY), Phospholipase D1 (PLD1), Stearoyl-CoA Desaturases 1 (SCD1), are closely related to cancer metastasis." (PMID 33718168, 2021).
cancer (continued). "We blocked the tumor anabolism with orlistat, lonidamine and DON (6-Diazo-5-oxo-L-norleucine) (OLD drug scheme) to inhibit FASN, HK2 and GLS, respectively, whereas with the combination of anti-catabolic drugs we aimed to ameliorate cancer cachexia." (PMID 33664364, 2021). "The dynamic metabolic dependency between CAFs and cancer epithelial cells has been shown to promote FAO and inhibit FAS due to decreased transactivation of FASN and FA binding proteins (FABPs) in epithelial cancer cells." (PMID 34638293, 2021). "The ion intensities of several FAs were found to be an increasing trend from the muscle to the epithelium to cancer tissue in ESCC, which was in good agreement with the expression of FASN, a critical metabolic enzyme for the de novo synthesis of FAs." (PMID 34568427, 2021). "Since Usp14 regulates the level of FASN in MPHs, we predicted that knockdown or inhibition of FASN and USP14 together would have a synergistic effect in reducing the proliferation of cancer cells." (PMID 34948233, 2021). "FASN, the only human lipogenic enzyme available for de novo FAS, has been widely reported to promote cancer progression." (PMID 34823530, 2021). "HPLC-MS/MS analysis showed that FASN, ACACA, α-tubulin, and β-tubulin were the target molecules, which SFN initiated anti-cancer signaling to downregulate." (PMID 34620841, 2021). "Key enzymes for lipid metabolism such as ATP citrate lyase (ACLY), fatty acid synthase (FASN), and stearoyl-CoA desaturase 1 (SCD1) can be differentially expressed in NSCLC compared to non-cancer tissue." (PMID 34822397, 2021). "These key de novo fatty acid synthesis enzymes, such as ACLY, ACC, FASN and SCD, have been found upregulated in different cancers." (PMID 34200820, 2021). "Oncogenic de novo lipogenesis, which is catalyzed by the overexpressed fatty acid synthase (FASN), is an important metabolic phenotype observed in many cancers." (PMID 34765544, 2021). "Overexpression of the deubiquitinase USP2a leads to stabilization of fatty acid synthase (FAS), the levels of which are often elevated in aggressive human cancers." (PMID 34956872, 2021). "Fatty acid synthase (FASN) is responsible for the catalysis of endogenous fatty acids and, therefore, is commonly upregulated in cancer cells (17, –, 19)." (PMID 33208446, 2021). "Up-regulation of lipid biosynthesis enzymes, including acetyl-CoA carboxylase (ACC), fatty acid synthase (FASN) and HMG-CoA reductase (HMGCR), has been reported in many cancers." (PMID 34421595, 2021). "Various evidence reported that an upregulation of lipid biosynthesis enzymes, including acetyl-CoA carboxylase (ACC), fatty acid synthase (FASN) and HMG-CoA reductase (HMGCR), can be found in many cancer types." (PMID 34421595, 2021). "A number of studies have shown that FASN inhibition decreases proliferation of malignant cells, induces apoptosis, and prevents EMT in various cancer models." (PMID 33673109, 2021). "Rate‐limiting enzymes for FAs synthesis, such as FASN, ACLY, and ACC, are significantly upregulated in cancer cells, and inhibition of these enzymes can decrease the proliferation and growth of cancer cells." (PMID 34766135, 2021). "In general, PCa-associated exosomes were found to be characterized by a cargo containing cancer-related proteins such as CD9, CD81, and TSG101, Annexin A2, Fatty Acid Synthase (FASN), and prostate-specific membrane antigen (PSMA)." (PMID 33800141, 2021). "FASN, ACC, and ACLY are downstream target genes of the SREBPs transcription factors that are upregulated in cancer cells." (PMID 34766135, 2021). "Similar kinds of manifestations were also noted in toxic control after MNU administration, i.e., the increase in HIF-1α, SREBP-1c, FASN but a decrease in PHD-2, which indicated the development of cancer hypoxia in these animals." (PMID 34090331, 2021). "There is evidence that an up-regulation of lipid biosynthesis enzymes, including ACC, FASN and HMGCR, can be found in many cancer types." (PMID 34421595, 2021).